SOCS3 (suppressor of cytokine signaling 3)
Diseases named in the same sentence as SOCS3 in open-access papers (continued):
Sharing a sentence is not in itself a finding about the gene and the disease.
tumor (continued). "Based on these findings, we hypothesized that a pro-glycolytic shift occurs in AMs within tumor-bearing lungs and is responsible for their impaired SOCS3 secretion." (PMID 41567211, 2025). "The pharmacologic inhibition of glycolysis, for instance, may restore SOCS3-mediated immunoregulation and limit tumor progression." (PMID 41567211, 2025). "By linking glycolytic reprogramming to impaired SOCS3 secretion, our study suggests that targeting metabolic pathways in AMs may represent a novel therapeutic approach to reinvigorate their tumor-suppressive functions." (PMID 41567211, 2025). "This, we reasoned, could result in decreased vesicular SOCS3 packaging/secretion and thereby contribute to tumor development and progression." (PMID 41567211, 2025). "Importantly, our findings implicate these metabolic changes in the disruption of SOCS3 secretion, a process critical for immune regulation and tumor surveillance." (PMID 41567211, 2025). "This suggests that in certain cellular contexts, as demonstrated with HCC44 cells, the depletion or inactivation of SOCS3 may further enhance the anti-tumor effect of PARP7 inhibition." (PMID 40493189, 2025). "Alveolar macrophages (AMs), the resident immune cells of the lung, play a critical role in maintaining pulmonary homeostasis, in part through the secretion of suppressor of cytokine signaling 3 (SOCS3)—a recognized tumor suppressor—within extracellular vesicles (EVs)." (PMID 41567211, 2025). "For example, IGF1R, PDK4, and SOCS3 are involved in tumor proliferation, migration, and invasion." (PMID 39618816, 2024). "The researchers suggested that uptake of exosomes containing miR-222-3p from GR tumor cells by other tumor cells could downregulate SOCS3, thereby enhancing the malignant phenotype, including increased proliferation, drug resistance, migration, and invasion." (PMID 39273095, 2024). "Thus, an increase in SOCS3 transcription in MBM exposed to factors released from JunBlo microglia cells can inhibit the STAT3-mediated pro-tumor effects." (PMID 37894348, 2023). "Thus, a key tumor suppression mechanism of SOCS1 is to prevent the tumor suppressors SOCS3 and CDKN1A from gaining oncogenic potential." (PMID 36765862, 2023). "Besides, SOCS3 mimetic have been shown to reduce tumor growth and inhibit lung metastasis in triple negative breast cancer (TNBC) by suppressing the production of inflammatory cytokines." (PMID 37025997, 2023). "The expression and function of SOCS3 vary significantly among different tumor types." (PMID 35226171, 2023). "For tumors, the function of SOCS3 depends on the tumor type." (PMID 36690663, 2023). "Loss of SOCS3 in SOCS1-deficient mice reduced the growth of DEN-induced HCC without affecting tumor incidence." (PMID 36765862, 2023). "SOCS1 and SOCS3 function as independent tumor suppressors in hepatocytes." (PMID 36765862, 2023). "This contradicts our result that higher expression of SOCS3 was observed in ccRCC tumor." (PMID 37762031, 2023). "Inhibition of tumor growth by blue LED light may also be related to the effects of SOCS3 and CRY1/2, which needs further verification." (PMID 36313662, 2022). "Our analysis also indicated that SOCS3 may be involved in tumor immune evasion via immune cell infiltration or T-cell exclusion across different types of cancer." (PMID 35600392, 2022). "Moreover, protein expression of SOCS3 was also downregulated in CRC tumor samples compared to that in non-tumor samples." (PMID 35184640, 2022). "Our research found that SOCS3 expression is relevant to tumor-promoting immune cells of almost all types of cancer; therefore, T-cell exclusion may be a primary mechanism of tumor immune cell infiltration." (PMID 35600392, 2022).
tumor (continued). "Lastly, we examined whether CD14CTX and CD4SOCS3 interact within the tumor microenvironment since we could also identify a population of SOCS3+CD4+ T cells in biliary tumors by scRNAseq." (PMID 36130508, 2022). "We found that conditional SOCS3 knockout in myeloid linage strikingly promoted tumor growth." (PMID 36329699, 2022). "Together, the results show that SOCS3 is an immuno-oncogenic molecule that may serve as a marker for tumor diagnosis, treatment, and prognosis, and thus, further experimental validation to ascertain its value is justified." (PMID 35600392, 2022). "Ablation of SOCS3 within the myeloid lineage was found to promote tumor development in mice." (PMID 34604264, 2021). "Recent studies indicated that SOCS3 could regulate immune checkpoint molecules to control response to immune cells such as macrophages and T cells, for example, the deletion of SOCS3 in T lymphocytes induced antitumor immunity in murine tumor models." (PMID 33659045, 2021). "Finally, constitutive activation of the suppressor of cytokine signaling-3 (SOCS3) is thought to protect tumor cells against interferon alpha (IFNα)-mediated growth inhibition." (PMID 34204115, 2021). "In addition, interference in SOCS3 expression in the colon promoted tumor growth in ApcminmiR-708−/− mice, indicating that the blocking effect of miR-708 deficiency on tumor growth was reversed by loss of SOCS3." (PMID 34934045, 2021). "WB and IHC were employed to verify the SOCS3/JAK2/STAT3 expression in the tumor tissues of mice." (PMID 34388111, 2021). "In addition, SOX2 has been shown to activate the JAK-STAT pathway, which regulates both immune response and tumor progression, while inhibiting SOCS3 and PTPN1, which are regulators of immune signaling." (PMID 34831420, 2021). "SOCS3 expression is reduced during progression from active UC to IBD-CRC and the altered methylation of SOCS3 may be involved in tumor progression increasing STAT3 signaling." (PMID 34744751, 2021). "The activation of STAT3 signaling and the inhibited expression of SOCS3 may be responsible for aggressive tumor growth in DNMT3b-positive ESCC cells." (PMID 34691358, 2021). "For example, SOCS3 was downregulated in the bonding group, yet it is a tumor suppressor for lung and other cancers, which may reflect responses related to oxytocin signaling during bonding." (PMID 33960931, 2021). "Blocking JAK/STAT3 signaling with SOCS3 might activate antitumor immunity in the tumor microenvironment." (PMID 34830179, 2021). "In our study, SOCS3 had lower expression levels in tumor tissues than in normal tissues." (PMID 34120621, 2021). "Furthermore, CD276 high expression and SOCS3 low expression in HCC tissue were significantly associated with high Edmondson grading (P=0.021) and age, tumor size (P=0.026, 0.041), respectively." (PMID 32742491, 2020). "Similarly, SOCS3 downregulation allows for persistence of STAT3 mediated signaling that is proposed to contribute to carcinogenesis by inducing multiple tumor-promoting genes." (PMID 30859089, 2019). "For example, miR-222-3p, implicated as a tumor promoter in diverse tumor types, activates macrophages to the M2 phenotype by downregulating suppressor of cytokine signaling-3 (SOCS3) which is a negative feedback regulator of the JAK/STAT signaling pathway." (PMID 31300030, 2019). "The absence of NK cells measured similar expression of Socs3 mRNA to WT groups, associated with tumor killing, but base levels of Tnf mRNA, a key pro-inflammatory cytokine in anti-tumor responses." (PMID 31117965, 2019). "Overexpression of SOCS3 had an anti-proliferative effect on breast cancer cells." (PMID 30787278, 2019). "This indicates that constitutive SOCS3 may play a role in tumor progression by blocking IFN-α mediated growth inhibition and decreasing overall sensitivity to cytokine signaling." (PMID 31684088, 2019).
tumor (continued). "MiR-203 as a tumor suppress gene, studies have found hepatic over-expression of miR-203 could facilitate the initiation of the liver by targeting SOCS3 through IL-6/STAT3 signaling pathway." (PMID 29670525, 2018). "Further analysis showed that SOCS3 expression was correlated with tumor differentiation degree, depth of invasion, TNM stage, and lymph node metastasis, implying that low SOCS3 expression was associated with other aggressive biological behaviors such as invasion and metastasis." (PMID 29662621, 2018). "whereas demethylation or recovery of SOCS-3 expression via approaches such as drug treatment can significantly inhibit the growth of tumor cells, suggesting that SOCS-3 may act as a tumor suppressor gene." (PMID 29662621, 2018). "Above data implied that tumor-derived IL-6 predominantly triggered SOCS3 suppression in e-MDSCs, and hence it could be reversed by using the IL-6R blocking antibody." (PMID 30083161, 2018). "Notably, the activation of STAT3 has strong negative feedback from SHP phosphatases and suppressor of cytokine signaling 3 (SOCS3), which is inhibited in tumor cells." (PMID 30104473, 2018). "Metformin treatment decreased the gene expression of Hif-1α and Socs-3, genes associated with cancer cell resistance to death, in B16F10 cells; these genes have been reported as targets of metformin in different tumor types." (PMID 29899823, 2018). "Furthermore, SOCS3 exhibits antitumor activity in a mesothelioma xenograft model, such as reducing tumor volume and tumor nodule weight and inducing tumor apoptosis." (PMID 28228755, 2017). "Finally, the administration of a SOCS3 mimetic peptide, corresponding to KIR-ESS domain of SOCS3 opposed IL-22 effects in transformed keratinocytes in vitro and counteracted tumor growth in mice." (PMID 28445952, 2017). "Suppressor of cytokine signaling 3 (SOCS3), a crucial negative regulator of the JAK/STAT signaling pathway, which might be associated with tumor malignant phenotypes, was identified as a potential target gene of miR-222-3p." (PMID 28743280, 2017). "All these results suggest that SOCS3 is a direct target of miR-222-3p, and exosomic miR-222-3p might enhance tumor malignancy through SOCS3 and its downstream effectors, such as the Jak2/Stat3 and Bcl-2 pathways." (PMID 28743280, 2017). "Silencing of SOCS3, through promotor hypermethylation is a common feature of cancer cells 3, 4, however, it is not yet known how the resulting “highly proliferative” cells escape anti‐tumour immunity." (PMID 28508554, 2017). "SOCS3 (suppressor of cytokine signaling 3), an important tumor suppressor, is often aberrantly inactivated in various tumors, but it is currently unclear whether SOCO3 is a target of miR-455-5p." (PMID 29383133, 2017). "The contribution of negative regulator suppressor of cytokine signaling-3 (SOCS3) promoter variants in HBV disease and SOCS3 hypermethylation in tumor tissues were investigated The SOCS3 promoter region was screened for polymorphisms in 878 HBV patients and in 272 healthy individuals." (PMID 28179578, 2017). "Additionally, overexpression of Flag-SOCS3 in H1299 cells with lower SOCS3 level, dramatically reduced cell proliferation, colony formation, cell migration and invasion, and tumor growth in vivo." (PMID 29383133, 2017). "IDO may dampen the immune response which can drive IEC hyperproliferation in the absence of SOCS3, demonstrating the intricate interplay of immune signals regulating mucosal homeostasis, and suggesting a novel tumour suppressor role of SOCS3." (PMID 28508554, 2017). "SOCS3 inhibited tumor cell proliferation, migration, and invasion in many tumor types." (PMID 29383133, 2017).
tumor (continued). "Additionally, GLI1, p-STAT3, STAT3, and SOCS3 were detected both in the tumor and the adjacent stromal tissues, indicating that the involvement of these proteins in the tumor microenvironment." (PMID 27275540, 2017). "Therefore, the present study focused on the similarity and disparity of the expression, distribution, function, and regulation of SOCS1 and SOCS3 between tumor cells and immune cells in the tumor microenvironment." (PMID 28228755, 2017). "However, considering the difference in the expression patterns of SOCS1 and SOCS3 in tumor cells and immunocytes, different therapeutic approaches should be implemented according to the types of target cells." (PMID 28228755, 2017). "The survival data suggest tumor growth is inhibited in mice with SOCS3 deletion in myeloid cells." (PMID 26967393, 2016). "Regarding the downregulation of IL-6 mediated by SOCS3 overexpression, as early as two hours after exposure to 15d-PGJ2, and considering the detrimental effects and actions of IL-6 linked with tumor growth, progression, and relapse, 15d-PGJ2 is presented as a novel antineoplastic drug." (PMID 27190500, 2016). "Modulation of SOCS3 in tumor-infiltrating myeloid cells may also contribute to an immunosuppressive environment that represses NK activity." (PMID 27148255, 2016). "Our recent studies suggested that enhanced expression of SOCS3 could reduce tumor metastasis, the expression of epithelial-to-mesenchymal transition (EMT) markers and STAT3 activation in the absence of interleukin-6 (IL-6) stimulation in CCA cell lines." (PMID 26485275, 2015). "Several studies support a role for SOCS3 as a tumor suppressor in different types of cancers." (PMID 26416445, 2015). "However, lower SOCS3 protein expression was observed in CCA tumor tissues than the corresponding peritumoral biliary tissues." (PMID 26485275, 2015). "Our recent studies found that high expression of SOCS3 could reduce tumor metastasis, EMT markers and STAT3 activation in the absence of IL-6 stimulation in CCA cell lines." (PMID 26485275, 2015). "SOCS3 is involved in the suppression of tumor growth and metastasis of HCC." (PMID 26447993, 2015). "The tumor tissues were obtained from all HCC patients to detection SOCS3 expressions." (PMID 26447993, 2015). "SOCS3 functions as a tumor suppressor in many cancers including GBM." (PMID 24633048, 2014). "SOCS-3 H-score emerged as an independent predictor of adverse prognosis, along with tumor stage." (PMID 24593195, 2014). "Likewise, exogenous expression of SOCS3 was found to significantly reduce tumour growth and potently enhance the efficacy of chemotherapy in vivo." (PMID 24757565, 2014). "Thus, SOCS3 is versatile, acting as tumor suppressor, tumor promoter, or immunomodulator according to context." (PMID 23372669, 2013). "Moreover, other evidence indicates that SOCS3 is localized both in the cytoplasm and nucleus in normal and tumor cell lines." (PMID 23028842, 2012). "It was of interest in the present study to investigate whether specifically IL11 regulated pSTAT3 and SOCS3 in cancer cells as both have been shown to be involved in numerous tumours." (PMID 20553623, 2010). "Emerging data in mice and humans suggest that Suppressor of Cytokine Signaling 3 (SOCS3) may act as a tumor suppressor in the intestine, and decreased SOCS3 expression may promote CRC." (PMID 20500855, 2010). "Evidence from previous studies point to activated STAT5 as a possible SOCS2, SOCS3 and CIS genes controller and its loss may result in less differentiated and more malignant tumours, and subsequently; poorer prognosis." (PMID 20433750, 2010). "Recent evidence in mice and humans suggest that the anti-inflammatory protein Suppressor of Cytokine Signaling 3 (SOCS3) may act as a tumor suppressor in the colon." (PMID 20500855, 2010). "More data was particularly evident in SOCS1 and SOCS3 roles as tumor suppressors." (PMID 20433750, 2010).
tumor (continued). "SOCS3 may regulate tumor development through various physiological and pathological processes." (PMID 40838069, 2025). "To determine whether elevated glycolysis is mechanistically responsible for the impaired SOCS3 secretion by AMs from tumor-bearing lungs, we treated the cells with the unmetabolizable glucose analog 2-DG to inhibit glycolysis and subsequently measured SOCS3 levels in their CM." (PMID 41567211, 2025). "Furthermore, scRNA-seq and spatial transcriptome analysis revealed high SOCS3 expression specifically in monocytes and macrophages, suggesting its potential role in mediating the activity of these immune cells to influence tumor progression and drug sensitivity in GBM." (PMID 41318472, 2025). "Additionally, IL-6 itself has been found to increase hypermethylation of SOCS3, all of which may contribute to a positive feedback loop in the H. pylori-infected tumor microenvironment." (PMID 38422751, 2024). "However, Pten, and Socs3 are tumor suppressors, and there are risks as treatment targets." (PMID 39695101, 2024). "Depending on the type of cancer, SOCS3 may function as a tumor suppressor or as a promoter." (PMID 37296634, 2023). "Therefore, inhibition of SOCS3 activity in macrophages may have a therapeutic effect on inhibiting tumor metastasis." (PMID 33224886, 2020). "The influence of SOCS3 on tumor progression may also occur through other signaling pathways." (PMID 31222560, 2019). "It is reported that increased miR-30a-mediated SOCS3 decrease was involved in MDSC function and differentiation, and miR-30a antagomir could inhibit the growth of tumor via upregulated SOCS3 to decrease MDSCs accumulation and immunosuppressive capacity in vivo." (PMID 30083161, 2018). "SOCS-1, SOCS-3 may have protective functions in tumor development." (PMID 30788302, 2018). "Thus, specific treatment targeting SOCS1 and SOCS3 might be considerably important in inhibiting tumor development and progression." (PMID 28228755, 2017). "Therefore, tumor-derived exosomal miR-203 may reduce expression of SOCS3 followed by induction of M2 macrophages and inhibition of M1 macrophages." (PMID 29108252, 2017). "Therefore importantly, our findings suggest that SOCS3 not only limits pro‐tumourigenic proliferative signals 2, 13, but may also mediate its tumour suppressive effects through limiting IDO production and thus maintaining effective immune surveillance." (PMID 28508554, 2017). "Thus, SOCS3 plays a tumor-suppressive function in NSCLC cells." (PMID 29383133, 2017). "This pathway could also have relevance to the related process by which cortical fracture healing occurs, and SOCS3-dependent pathways could be targeted to promote corticalization at fracture sites, or to protect cortical bone structure in the context of tumor metastasis." (PMID 28993616, 2017). "Indeed, tumor cells can develop resistance mechanisms that favour cancer growth, and the compromised expression of SOCS3 in response to IL-22 might be representative of this situation." (PMID 28445952, 2017). "We found that SOCS3 knockdown in H460 cells with higher level of SOCS3, significantly promoted cell proliferation, anchorage-independent growth (3 fold), cell migration and invasion, and tumor growth in vivo, suggesting a tumor-suppressive role of SOCS3 in NSCLC cells." (PMID 29383133, 2017). "However, it is not well known whether the anti-tumor effect of FXR involves the regulation of SOCS3 or STAT3." (PMID 26416445, 2015). "However, it is unclear whether the tumor suppressive activity of FXR involves the regulation of SOCS3." (PMID 26416445, 2015).